METTL1 (methyltransferase 1, tRNA methylguanosine)
Diseases named in the same sentence as METTL1 in open-access papers (continued):
Sharing a sentence is not in itself a finding about the gene and the disease.
prostate carcinoma (15 papers, 2023 to 2025). A carcinoma that arises from epithelial cells of the prostate gland. "The abnormal increase in CDK14 levels in prostate cancer is linked to METTL1-mediated modification of its mRNA expression in an m7G manner, resulting in enhanced CDK14 mRNA stability." (PMID 40809690, 2025). "Reducing METTL1 expression in prostate cancer models results in increased proinflammatory immune cell infiltration and improves the response to immunotherapy, suggesting METTL1 as a potential target to improve chemotherapy sensitivity." (PMID 39802639, 2025). "In prostate cancer, METTL1 plays a role in regulating the levels of interferons and immune factors in the immune microenvironment through m7G modification." (PMID 40809690, 2025). "In prostate cancer models, METTL1 knockdown significantly increases the infiltration of proinflammatory immune cells within tumors and enhances immunotherapy efficacy." (PMID 41562049, 2025). "In HCC, CRC, BRCA, prostate cancer, and ICC, high METTL1 expression is consistently associated with immunosuppressive tumor microenvironments, immune evasion, and poor prognosis." (PMID 41562049, 2025). "For example, METTL1 knockout in prostate cancer elicits a cytotoxic immune response and increases the infiltration of cytotoxic CD8+ T cells." (PMID 38918785, 2024). "Immunohistochemical analysis confirmed high expression of METTL1 in luminal (K18 +) cells in human prostatic carcinoma samples." (PMID 37660182, 2023). "Knockdown of Mettl1 in prostate cancer preclinical models increases intratumoural infiltration of pro-inflammatory immune cells and enhances responses to immunotherapy." (PMID 37516825, 2023). "Our study provides compelling evidence of METTL1's oncogenic function and overexpression in prostate cancer (PCa)." (PMID 37516825, 2023). "To validate the methylation of tRNAs by METTL1 in prostate cancer (PCa) cells (PC3), we developed a high-throughput method that precisely maps m7G deposition in RNA." (PMID 37660182, 2023). "However, in prostate cancer, METTL1-mediated m7G modification induces M2 polarization of macrophages, indicating the heterogeneity of METTL1 functions in different tumors." (PMID 39372415, 2024). "Notably, in prostate cancer, METTL1 stabilizes CDK14 mRNA by catalyzing internal m7G modification, resulting in the upregulation of CDK14, which in turn promotes tumor cell proliferation and invasion." (PMID 38385078, 2024). "In prostate cancers, researchers found that METTL1-mediated tRNA m7G modification could impede the biogenesis of tRNA fragment, consequently diminishing the translation of transcripts associated with IFN signaling pathway and promote macrophage polarization towards the M2 phenotype 123." (PMID 38385078, 2024). "Immunohistochemical analysis further revealed that Mettl1 expression was higher in murine PCa and was highly expressed in luminal cells, which are the most common epithelial cell type and are generally accepted as the preferred cell of origin for human prostate cancer." (PMID 37516825, 2023). "In view of the important role of SP1 in the transcriptional regulation of genes crucial for prostate cancer, we constructed cell lines with stable knockdown of SP1 in LNCaP-AI and C4-2 and found that silencing of SP1 decreased the expression level of METTL1." (PMID 37599359, 2023). "In our study, we have identified METTL1, by modulating mRNA translation, is a crucial regulator of the IFN-STAT1 signalling pathway in tumour cells, implying its significance in prostate cancer and the tumour microenvironment." (PMID 37516825, 2023). "However, there are no reports of METTL1 being associated with tumors in prostate cancer." (PMID 37599359, 2023). "To elucidate the effect of METTL1 on the malignant biological behavior of CRPC, we implemented phenotypic experiments in prostate cancer cell lines." (PMID 37599359, 2023).
prostate carcinoma (continued). "Prior investigations have suggested that the classical m7G writer METTL1 may undergo transcriptional upregulation by the transcription factor (TF) SP1, thereby stabilizes CDK14 mRNA and contributes to the progression of prostate cancers." (PMID 38385078, 2024). "However, the role of m7G modifications within mRNA and its “writer” methyltransferase 1(METTL1) in tumors, particularly prostate cancer (PCa), has not been revealed." (PMID 37599359, 2023). "To date, only a few reports have examined the potential functions of METTL1 in immunotherapy for prostate cancer and ICC, while systematic pan-cancer analyses-such as evaluating the correlation between METTL1 expression and ICI efficacy using TCGA datasets-are lacking." (PMID 41562049, 2025).
esophageal squamous cell carcinoma (13 papers, 2022 to 2026). Esophageal squamous cell carcinoma (ESCC) is a type of esophageal carcinoma (EC) that can affect any part of the esophagus, but is usually located in the upper or middle third. "METTL1 is significantly up-regulated in esophageal squamous cell carcinoma, and its mediated tRNA m7 G modification promotes malignant progression of esophageal squamous cell carcinoma through the RPTOR/ULK 1/autophagy axis, and its high expression is associated with poor prognosis of patients." (PMID 39289775, 2024). "METTL1/WDR4 are significantly up-regulated in esophageal squamous cell carcinoma (ESCC), and silencing any of these genes lowers m7G-tRNA modification." (PMID 38201505, 2023). "Here we reveal that tRNA m7G methyltransferase complex proteins METTL1 and WDR4 are significantly up-regulated in esophageal squamous cell carcinoma (ESCC) tissues and associated with poor ESCC prognosis." (PMID 35304469, 2022). "For example, in esophageal squamous cell carcinoma (ESCC), METTL1 promotes tumor progression through the regulation of RPTOR gene translation." (PMID 41501031, 2026). "Further analysis revealed that METTL1 and WDR4 are upregulated in esophageal adenocarcinoma (EAC) samples and further increased in esophageal squamous cell carcinoma (ESCC) samples." (PMID 35304469, 2022). "In esophageal squamous cell carcinoma (ESCC), researchers demonstrated that METTL1 and WDR4 could induce the translation of RPTOR and decrease autophagic flux in ESCC cells." (PMID 38385078, 2024).
glioblastoma (12 papers, 2021 to 2025). The most malignant astrocytic tumor (WHO grade IV). "The loss of METTL1 results in decreased m7G tRNA methylation and expression, inhibition of cell cycle and global translation, as well as the growth of tumors cell in many types, such as melanoma, liposarcoma (LPS), glioblastoma multiforme (GBM), and acute myeloid leukemia (AML)." (PMID 36923941, 2023). "METTL1 knockdown inhibits the growth of a variety of tumors, including glioblastoma, melanoma, and AML." (PMID 39019857, 2024). "Both METTL1 and IGF2BP3 are highly expressed in glioblastoma, and their upregulations are associated with poor survival in patients." (PMID 39198433, 2024). "Analysis of TCGA datasets revealed that METTL1 is frequently amplified and overexpressed in various human cancers, such as glioblastoma and sarcoma." (PMID 35986847, 2022). "Specifically, the high expression of METTL1, as the tRNA methyltransferase, could impact translation in glioblastoma and neuroblastoma through modulating levels of m7G-modified tRNAs27,28." (PMID 39198433, 2024). "Similar to METTL1, IGF2BP3 is highly expressed in tumors compared to normal tissues across various cancer types, with glioblastoma ranked second." (PMID 39198433, 2024). "Among them, METTL1 had high-level amplifications above 5% in five TCGA tumor types: lung adenocarcinoma (LUAD, 5.29%), glioblastoma (GBM, 13.57%), sarcoma (SARC, 17.00%), adrenocortical carcinoma (ACC, 6.74%), and cholangiocarcinoma (CHOL, 5.56%)." (PMID 34285249, 2021). "We found that METTL1 expression was lower in responders than in non-responders to ICB therapy in breast, colorectal, ovarian cancer, and glioblastoma patients, suggesting that high METTL1 expression predicted poor response to ICB therapy." (PMID 37516825, 2023).
liver cancer (12 papers, 2021 to 2025). An epithelial or non-epithelial malignant neoplasm that arises from the liver. "The results showed that METTL1 was upregulated in most cancers, including liver cancer (LIHC) and bile duct cancer (CHOL)." (PMID 39616161, 2024). "In liver cancer, researchers uncovered that METTL1-meditated m7G tRNA modification facilitated intrahepatic cholangiocarcinoma progression by promoting EGFR translation." (PMID 39616161, 2024). "In summary, the methylation modification of RNA m7G mediated by the methyltransferase METTL1 plays an indispensable role in the growth, invasion and malignant phenotypic transformation of liver cancer cells." (PMID 34778277, 2021). "Mechanistically speaking, overexpression of METTL1 promotes the proliferation and migration of liver cancer cells, while knockout of METTL1 leads to the opposite phenotype, possibly because METTL1-mediated RNA m7G methylation inhibits phosphatase and tensin homolog (PTEN) signal transduction." (PMID 34778277, 2021). "Among the genes associated with the prognosis of liver cancer, the genes associated with shorter survival period are AGO2, DCPS, IFIT5, LARP1, NCBP2, NUDT10, and NUDT16; the genes associated with longevity are EIF4E3, EIF4G3, METTL1, NCBP1, NSUN2, NUDT11, NUDT4, and WDR4." (PMID 36845384, 2023). "In two other studies, the METTL1 / WDR4 mediated modification of tRNA m7G methylation promotes lung and liver cancer progression." (PMID 37528384, 2023). "However, METTL1 or WDR4 interacting mRNAs and lncRNAs have rarely been studied in liver cancer." (PMID 37528384, 2023).
acute myeloid leukemia (11 papers, 2022 to 2026). Acute myeloid leukemia (AML) is a group of neoplasms arising from precursor cells committed to the myeloid cell-line differentiation. "Notably, METTL1-mediated m7G modification drives leukemogenesis in acute myeloid leukemia (AML) by reprogramming tRNA-dependent translational control, illustrating how epitranscriptomic dysregulation interfaces with oncogenic pathways." (PMID 40565315, 2025). "In acute myeloid leukemia (AML) patients, the Methyltransferase 1/WD repeat domain 4 (METTL1/WDR4) complex catalyzes m7G modification of tRNA, enhancing translation efficiency of specific mRNAs (e.g., HOXA9, MEIS1) to maintain AML cell proliferation and stemness." (PMID 41550494, 2026). "In acute myeloid leukemia (AML), the knockout of METTL1 reduces the m7G methylation level of mRNA and tRNA, resulting in a significant decrease in protein synthesis." (PMID 39155349, 2024). "However, the functions and molecular mechanisms of METTL1/WDR4 in acute myeloid leukemia (AML) remain to be determined." (PMID 38268051, 2024). "Recently, some methyltransferase-like (METTL) proteins have been found to play crucial roles in the development of acute myeloid leukemia (AML) through mediating RNA modifications, such as METTL3/14/16 mediated N6-methyladenosine (m6A) and METTL1 mediated N7-methylguanosine (m7G)." (PMID 40382345, 2025).
osteosarcoma (11 papers, 2024 to 2025). A usually aggressive malignant bone-forming mesenchymal neoplasm, predominantly affecting adolescents and young adults. "METTL1 is frequently amplified in osteosarcoma and is associated with poor patient prognosis." (PMID 39979979, 2025). "A recent study revealed that METTL1 increases osteosarcoma chemoresistance to doxorubicin by altering oncogenic mRNA translation." (PMID 39979979, 2025). "METTL1 knockdown decreases the tRNA m7G modification level and impairs osteosarcoma progression, whereas METTL1 overexpression promotes osteosarcoma proliferation, migration and invasion." (PMID 39979979, 2025). "Studies have revealed that METTL1 overexpression enhances the migrative and invasive abilities of osteosarcoma and adrenocortical carcinoma (ACC) cells." (PMID 39979979, 2025). "Knockdown of METTL1 results in reduced levels of tRNA m7G modification and impairs osteosarcoma proliferation in vitro and in vivo." (PMID 39289775, 2024). "In osteosarcoma, METTL1 is highly expressed in osteosarcoma and correlates with poor patient prognosis." (PMID 39289775, 2024). "Interestingly, decreased levels of METTL1 have been observed in osteosarcoma, with low METTL1 expression playing an oncogenic role through the regulation of ferroptosis mediated by the pri-miR-26a/FTH1 axis." (PMID 39870616, 2025). "In addition, METTL1 promoted chemotherapy resistance to doxorubicin in Osteosarcoma, and mediated resistance to anlotinib in OSCC." (PMID 41194259, 2025). "Thus, more experimental evidence is needed to clarify the specific function of METTL1 in osteosarcoma." (PMID 39979979, 2025). "However, another study revealed that METTL1 expression is markedly lower in osteosarcoma tissues than in normal bone tissues and that METTL1 expression decreases with increasing clinical stage." (PMID 39979979, 2025). "A recent study reported that METTL1 triggers osteosarcoma cells ferroptosis via the miR-26a/FTH1 axis which in turn induces iron death and increases the sensitivity of osteosarcoma cells to chemotherapeutic agents." (PMID 38822363, 2024). "Interestingly, another study revealed that METTL1 reduces the FTH1 protein level by targeting pri‐miR‐26a and FTH1, evoking ferroptosis and promoting the sensitivity of osteosarcoma cells to chemotherapeutic treatments." (PMID 39979979, 2025). "However, METTL1/pri‐miR‐26a/ferritin heavy chain (FTH1) axis signalling enhances ferroptosis in osteosarcoma and strengthens the sensitivity of osteosarcoma cells to chemotherapeutic drugs." (PMID 39979979, 2025). "METTL1 stimulates osteosarcoma malignancy by augmenting mRNA translation of lysyl oxidase‐like 2 (LOXL2), a key downstream target of METTL1 that is required for its function in osteosarcoma." (PMID 39979979, 2025). "METTL1 can upregulate mature miR-26a-5p, which then inhibits FTH1 mRNA translation efficiency; the decrease of FTH1 in turn increases ferroptosis and promotes chemotherapy sensitivity in osteosarcoma cells." (PMID 40725394, 2025). "METTL1 decreases FTH 1 expression by enhancing m7G modification of FTH 1 and pri-miR-26a, and thus increase ferroptosis, thereby reducing chemoresistance of osteosarcoma, so targeted therapy on METTL1 may be a potential and promising treatment strategy for osteosarcoma." (PMID 38654314, 2024).
breast cancer (10 papers, 2021 to 2026). A primary or metastatic malignant neoplasm involving the breast. "Given that CDK4/6 inhibitors are primarily employed in the luminal A/B (ER+) breast cancer subtype, METTL1 appears to be closely associated with this subtype." (PMID 41501031, 2026). "In breast cancer, METTL1-mediated m7G tRNA modification is necessary for codon recognition during mRNA translation." (PMID 41501031, 2026). "Recent studies indicate that METTL1-mediated tRNA m7G modification plays a crucial role in breast cancer cell proliferation, cell cycle regulation, and therapeutic response." (PMID 41562049, 2025). "In breast cancer, tRNA m7G modifications are essential for tRNA functionality; however, the biological role of METTL1-mediated tRNA m7G in BRCA remained unclear." (PMID 41562049, 2025). "Functionally, METTL1 exerts its effects in an enzymatic activity-dependent manner, suppressing breast cancer cell proliferation and arresting cell cycle progression." (PMID 41562049, 2025). "Breast cancer cell proliferation, migration, and invasion are decreased when METTL1 is silenced through upregulating EGFR/EFEMP1." (PMID 38201505, 2023). "Collectively, these findings indicate that METTL1 may exert distinct effects across different breast cancer subtypes." (PMID 41501031, 2026). "Overall, these findings reveal a tumor-suppressive role of METTL1-mediated tRNA m7G modification in breast cancer, selectively promoting translation of GADD45A and RB1 to induce G2/M cell cycle arrest, suggesting a potential strategy to improve CDK4/6 inhibitor therapy." (PMID 41562049, 2025). "While METTL1 exhibits clear oncogenic activity in certain malignancies, such as ICC and HCC, where it promotes tumor proliferation, metastasis, and immune evasion, studies have also reported potential tumor-suppressive roles of METTL1 in other cancers, including breast cancer." (PMID 41562049, 2025). "However, the biological functions of methyltransferase-like 1 (METTL1)-regulated m7G tRNA modifications in breast cancer (BC) remain largely obscure." (PMID 38822363, 2024). "Notably, the expression of METTL1 is adversely correlated with the prognosis of patients with breast cancer." (PMID 38201505, 2023). "Research has shown that components of the tRNA m7G methyltransferase complex, METTL1 and WDR4, are downregulated at both mRNA and protein levels in breast cancer tissues." (PMID 41562049, 2025). "In addition, METTL1 inhibited breast cancer (BC) cell cycle progression and proliferation by promoting the translation of growth arrest and DNA damage 45 alpha (GADD45A) and retinoblastoma protein 1 (RB1) mRNAs, selectively blocking the G2/M phase of the cell cycle." (PMID 39979979, 2025). "METTL1 enhances the translation of GADD45A and RB1 through an m7G dependent, codon-specific mechanism that increases tRNA-m7G levels, thereby inducing G2/M arrest and suppressing breast cancer cell proliferation while increasing the antitumor efficacy of CDK4/6 inhibitors such as abemaciclib." (PMID 41501031, 2026).